ME1 (malic enzyme 1)
Description:
Catalyzes the oxidative decarboxylation of (S)-malate in the presence of NADP(+) and divalent metal ions, and decarboxylation of oxaloacetate.
Synonyms: HUMNDME; MES
Tractability: Small molecule: a structure with a bound ligand is known; a high-quality ligand is known; it has a high-quality binding pocket; it belongs to a druggable protein family. PROTAC: ubiquitination databases record sites on it; its protein half-life has been measured; a small molecule that binds it is known.
Target class: Enzyme
Gene: Protein-coding gene on chromosome 6 (83,210,393 to 83,431,208, reverse strand). Ensembl gene ENSG00000065833.
Subcellular location: Cytoplasm
Subcellular location (Human Protein Atlas): Nucleoplasm; Plasma membrane; Cytosol
Pathways (Reactome):
Metabolism: PPARA activates gene expression; Pyruvate metabolism; Regulation of pyruvate metabolism
Cellular responses to stimuli: NFE2L2 regulating TCA cycle genes
Gene Ontology:
Molecular function: identical protein binding; magnesium ion binding; malate dehydrogenase (decarboxylating) (NADP+) activity; malic enzyme activity; manganese ion binding; oxaloacetate decarboxylase activity; protein binding; ADP binding; electron transfer activity; NAD binding; NADP binding; oxidoreductase activity, acting on the CH-OH group of donors, NAD or NADP as acceptor
Biological process: malate metabolic process; NAD+ metabolic process; NADP+ metabolic process; protein homotetramerization; regulation of NADP metabolic process; carbohydrate metabolic process; nucleotide biosynthetic process; response to carbohydrate; response to hormone
Cellular component: cytoplasm; cytosol; mitochondrion
Genetic constraint (gnomAD): Loss-of-function variants: 27 observed, 30.06 expected, observed/expected ratio (o/e) 0.9, 90% interval 0.66 to 1.24. The upper end of that interval is the gene's LOEUF score, 1.24, which puts it in group 5 of 6, group 1 being the genes least tolerant of losing a copy. Missense variants: 437 observed, 412.47 expected, observed/expected ratio (o/e) 1.06, 90% interval 0.98 to 1.15. Synonymous variants: 152 observed, 140.12 expected, observed/expected ratio (o/e) 1.08, 90% interval 0.95 to 1.24.
Homologues: Orthologues: chimpanzee ME1 (99% identical), macaque ME1 (98% identical), rabbit ME1 (95% identical), dog ME1 (93% identical), pig ME1 (93% identical), rat Me1 (91% identical), mouse Me1 (90% identical), guinea pig ME1 (81% identical), tropical clawed frog me1 (76% identical), zebrafish me1 (72% identical), Drosophila melanogaster Men (57% identical), Drosophila melanogaster Men-b (54% identical), and 4 more. Paralogues in human: ME3 (71% identical), ME2 (54% identical).
Diseases named in the same sentence as ME1 in open-access papers:
ME1 is named in the same sentence as 92 diseases in open-access papers, as found by Europe PMC text mining. Sharing a sentence is not in itself a finding about the gene and the disease. The quoted sentences say what the papers report.
breast cancer (15 papers, 2009 to 2025). A primary or metastatic malignant neoplasm involving the breast. "As anticipated, high ME1 expression was associated with a large tumor size of breast cancer patients." (PMID 30425310, 2018). "ME1 is particularly associated with the malignant phenotypes of basal-like breast cancer." (PMID 39996805, 2025). "ME1 is known to increase lactate production and glucose uptake in breast cancer cells, leading to glycolytic metabolism." (PMID 40857407, 2025). "ME1 is involved in several cancers, including gastric cancer, breast cancer, CRC, HCC, bladder cancer, and OSCC." (PMID 39996805, 2025). "Recent studies have shown that ME1 contributes to the progression of several cancers, such as oral squamous cell carcinoma, breast cancer, colorectal cancer, gastric cancer, lung cancer, and nasopharyngeal carcinoma." (PMID 34427987, 2021). "These clinical validations support the potential use of ME1 as a newly prognostic indicator and therapeutic target for breast cancer patients." (PMID 30425310, 2018). "Our previous work suggests that de novo fatty acid synthesis supports central carbon metabolism via redox coupling with malic enzyme 1 catalyzed conversion of malate to pyruvate in HER2-positive breast cancer cells." (PMID 29898756, 2018). "Although there is evidence to support an oncogenic role for ME1, its contribution is poorly studied in breast cancer and its distinct subtypes." (PMID 30425310, 2018). "Consistently, analysis of patient-derived breast cancer cell lines (CCLE dataset) showed that 25% (12/48) of cell lines have ME1 copy number amplification, 66.67% (8/12) of which belonged to BLBC subtype." (PMID 30425310, 2018). "We observed that ME1 was amplified in breast cancer, with 5.7% and 15.4% of primary breast tumors having ME1 amplification in MEBTABRIC dataset and TCGA dataset, respectively." (PMID 30425310, 2018). "In breast cancer patients, ME1 expression is positively correlated with large tumor size, high grade, poor survival, and chemotherapy resistance." (PMID 30425310, 2018). "To identify a possible association between ME1 expression and clinical oncology, we first assessed the correlation between ME1 expression and tumor size of breast cancer patients in NKI295 dataset." (PMID 30425310, 2018). "Previous work using rodent models found inhibitory effects of dietary SPI on: a) colon and mammary cancers, b) hepatosteatosis, c) adipose tissue deposition, and d) mammary and liver ME1 expression." (PMID 23056418, 2012). "Furthermore, ME1 expression significantly enhances the growth and invasion of cancer cells in basal-like breast cancer." (PMID 40510340, 2025). "Other regulators of ME1 expression include the canonical Wnt signaling pathway in breast cancer, dietary factors such as a high-fat diet in intestinal and hepatic tissues, and signaling through peroxisome proliferator-activated receptor (PPAR)/early growth response protein 4 (EGR4)." (PMID 39996805, 2025). "Similarly, analysis of the scRNA-seq data from the BRCA_GSE114727_inDrop dataset revealed 23 cell clusters and 11 cell types in breast cancer tissues, where ME1 was enriched in both monocytes/macrophages and myofibroblasts." (PMID 40510340, 2025). "Furthermore, the infiltration of immune cells was significantly reduced when they were co-cultured with breast cancer cells with ME1 knockdown." (PMID 38445776, 2024). "Biological function analysis revealed ME1 knockdown could significantly suppress the growth of breast cancer cells and influence its migration ability." (PMID 38445776, 2024). "Here, our results revealed ME1 expression was significantly upregulated in breast cancer, especially in patients with oestrogen receptor/progesterone receptor-negative and human epidermal growth factor receptor 2-positive breast cancer." (PMID 38445776, 2024).
breast cancer (continued). "In addition, it has been observed that ME1 expression is positively correlated with larger tumour size, higher grade, poorer survival, and chemotherapy resistance in breast cancer patients." (PMID 32273943, 2020). "Although ME1 overexpression highly correlated with larger tumor size and higher tumor grade in breast cancer patients, it didn’t significantly affect metastatic status of breast cancer through analyzing the correlation between ME1 expression and metastatic status in NKI295 and TCGA datasets." (PMID 30425310, 2018). "Indeed, ME1 expression was elevated in triple-negative breast cancer, and significantly downregulated in luminal subtype of breast cancers." (PMID 30425310, 2018). "Given the critical roles of ME1 expression in breast cancer, we performed Kaplan-Meier analyses to evaluate whether ME1 is a prognostic indicator for clinical outcomes by analyzing NKI295 and GSE25066 datasets." (PMID 30425310, 2018). "Our soft-agar assay showed ME1 expression contributed to colony-formation of breast cancer cells, indicating that ME1 might promote a more stem-like phenotype." (PMID 30425310, 2018). "In summary, ME1 plays an oncogenic role in the growth of breast cancer; it may serve as a potential biomarker of progression and constitute a therapeutic target in patients with breast cancer." (PMID 38445776, 2024). "For instance, overexpression studies have found that ME1 promotes cancer growth and metastasis via NADPH homeostasis in various cancers including gastric cancer, basal-like breast cancer and lung cancer, etc.." (PMID 39185122, 2024). "In this study, using TCGA data, HSD17B7, ACADL, ME1, MAOA, and TDO2 were identified as the top five DEGs related to FA metabolism in breast cancer tissues." (PMID 36936412, 2023). "In the clinic, aberrant high ME1 expression is specifically observed in BLBC subtype, and highly correlates with larger tumor size and higher grade in breast cancer patients." (PMID 30425310, 2018). "ERBB2-positive breast cancer cells are sensitive to inhibition of both FASN and malic enzyme 1 genes (Kourtidis A, Carkner RD, Eifert C, Brosnan MJ, Conklin DS; unpublished data)." (PMID 19298655, 2009). "In breast cancer, ME1 overexpression correlates with proliferation, lymph node metastasis, vascular invasion, and poor prognosis." (PMID 39996805, 2025). "Studies have shown that ME1 expression is higher in breast cancer tissues than in adjacent non-tumor tissues." (PMID 36936412, 2023). "To investigate the effect of CNVs on ME1 expression, we analyzed copy number alterations of breast cancer in two publicly available datasets (MEBTABRIC and TCGA), which contain: 1904 and 507 breast cancer patients, respectively." (PMID 30425310, 2018).
gastric cancer (10 papers, 2019 to 2025). A primary or metastatic malignant neoplasm involving the stomach. "Investigation of the role of ME1 in gastric cancer reveals that knockdown of ME1 is associated with elevated ROS and decreased NADPH levels in glucose limiting conditions." (PMID 32408513, 2020). "ME1 has been reported to be associated with poor survival in gastric cancer patients, and it may be an oncogene." (PMID 33903282, 2021). "Furthermore, aberrant ME1 gene expression was associated with poor prognosis of gastric cancer." (PMID 31881713, 2019). "In gastric cancer, ME1 promotes cell proliferation and metastasis, and its overexpression in CRC is associated with cancer progression, while it promotes colon carcinogenesis in ApcMin/+ mice." (PMID 39996805, 2025). "In gastric cancer, ME1 has also a key function in providing NADPH for glutathione and ROS homeostasis, which was critical for cancer cell survival under energy stress conditions, such as glucose limitations." (PMID 31881713, 2019). "One of the miRNAs dysregulated in PC and targeting KRAS is hsa-miR-885-5p, which has previously been reported as a tumour suppressor in hepatocellular carcinoma by regulating AEG1 and as an inhibitor of invasion and metastasis in gastric cancer by regulating ME1." (PMID 39057123, 2024). "In gastric cancer, ME1 promotes cell growth and metastasis by regulating NADPH homeostasis." (PMID 36671526, 2023). "Accordingly, ME1 knockdown in human gastric cancer cells suppressed tumor growth in vivo." (PMID 34884868, 2021). "Inhibition of ME1 leads to a decrease in NADPH (functioning as an antioxidant) and an increase in ROS, and consequently, is lethal in ME2-unexpressed human gastric cancer cells." (PMID 34884868, 2021).
Obesity (9 papers, 2010 to 2024). Accumulation of substantial excess body fat. "In our previous work, a global Me1 mutation (resulting in loss of ME1 protein expression) protected male C57BL/6 mice against high fat diet-induced obesity and associated sequelae, including hyperleptinemia, hyperinsulinemia, and hepatosteatosis." (PMID 37047583, 2023). "The targeted analysis of a subset of jejunum genes in the context of obesity and ME1 expression revealed novel, positive associations of ME1 with two key mediators of intestinal tissue architecture, inflammation, and metabolism, namely TLR9 and FFAR3." (PMID 37047583, 2023). "Regardless of the underlying mechanism, use of the SPI-HF diet enabled examination of effects of Me1 mutation on female mouse obesity and accompanying sequelae." (PMID 37047583, 2023). "Previous studies have reported robust associations of liver and adipose tissue ME1 with susceptibility to both diabetes and obesity in humans and rodent models." (PMID 25402228, 2014). "Recent studies with mice and humans have linked liver- and adipose-expressed ME1 with pre-disposition to obesity and type 2 diabetes." (PMID 23056418, 2012). "Further, we recently provided direct experimental support for the involvement of Me1 in obesity-related phenotypic characteristics and in gene networks associated with obesity using a Me1 knockout (Me1−/−) mouse model." (PMID 20463879, 2010). "For example, a study in rats with ME1 deficiency found that ME1 may promote adiposity and hepatic steatosis and induce circulating insulin and leptin, supporting the therapeutic targeting of ME1 for obesity, diabetes, and hepatic steatosis." (PMID 38836220, 2024). "Given that female C57BL/6 mice are not normally responsive to a high-fat diet, relative to male mice, we used this dietary paradigm to evaluate if a mutant Me1 allele (present in the homozygous state in the MOD-1 mouse line) would be protective against developing obesity." (PMID 37047583, 2023). "We hypothesized that an increased level of intestinal ME1 would promote intestinal cell proliferation and lipogenic pathway gene expression, as well as induce metabolic alterations and predisposition to obesity and hepatosteatosis." (PMID 25402228, 2014). "Previous work has correlated liver and adipose ME1 expression with susceptibility to obesity and diabetes; however, the contributions of intestine-expressed ME1 to these conditions are unknown." (PMID 25402228, 2014). "With the many tie-ins of ME1 with pathophysiology, the search for small molecule inhibitors of ME1 with tissue-selectivity and actions may, in due course, yield useful and multipurpose drugs to treat obesity and associated co-morbidities." (PMID 37047583, 2023). "Intestinal ME1 may thus constitute a therapeutic target to reduce obesity-associated pathologies." (PMID 25402228, 2014). "Data suggest that the pharmacological targeting of ME1 or the inclusion of soy protein in the diet may provide avenues to reduce obesity and its associated pro-tumorigenic endocrine environment and improve insulin sensitivity, potentially disrupting the obesity-colon cancer connection." (PMID 23056418, 2012). "Results document an integrative role for ME1 in development of female obesity, suggest novel linkages with specific pathways/genes, and further support the therapeutic targeting of ME1 for obesity, diabetes, and fatty liver disease." (PMID 37047583, 2023). "We examined the contribution of ME1 to the development of obesity by provision of an obesogenic diet to C57BL/6 wild type (WT) and MOD-1 (lack ME1 protein) female mice." (PMID 37047583, 2023). "Collective results provide support for intestinal ME1 impacting liver lipid and cholesterol metabolism and the regulatory linkage between these two tissues to influence obesity and insulin resistance." (PMID 25402228, 2014).
Obesity (continued). "We previously reported that mice functionally null for ME1 (MOD-1 mouse line) are protected from diet-induced obesity and exhibit reduced cell proliferation in colon and small intestine." (PMID 25402228, 2014). "The role of Me1 in obesity, energy homeostasis and diabetes has been well documented in the literature." (PMID 20463879, 2010). "Although high levels of ME1 expression may improve the cytoplasmic redox state in the liver, ME1 expression in WAT is positively correlated with increased lipogenesis and adipocyte volume, consistent with a causative role in obesity." (PMID 39061889, 2024). "In this regard, mice that are functionally null for ME1 (MOD-1 mouse line) are protected from diet-induced obesity and hepatosteatosis, and had reduced serum insulin and leptin concentrations as well as lowered levels of proliferation markers in the small intestine." (PMID 25402228, 2014). "Results support the premise that, in a mouse model of obesity, ME1 is an important physiological regulator of crosstalk among multiple signaling pathways, regardless of gender, suggesting its potential value as a targeted therapy for obesity, diabetes, fatty liver disease, and cancer in humans." (PMID 37047583, 2023). "Therefore, the Me1−/− mice appeared to be resistant to both diabetes and obesity development." (PMID 20463879, 2010). "Except for these and alcohol dehydrogenase 1B (ADH1B), malic enzyme 1 (ME1) and ethylmalonyl-CoA decarboxylase (ECHDC1), other expressed genes in the cluster have little known information in the context of obesity and chronic diseases." (PMID 30380678, 2018). "The knockout of ME1, a major cytoplasmic NADP+-reducing enzyme in WAT and a contributor to the reduction of cytoplasmic NADP+ to NADPH in the liver, led to decreased liver steatosis, fat mass, and obesity, and improvement in glucose tolerance." (PMID 39061889, 2024). "It is possible that intestinal ME1 overexpression affects blood glucose in the initial stages of diet-induced obesity, but that this effect is not maintained because chronic high-fat diet may eventually cause frank hyperglycemia, thus, obviating the genotype effect." (PMID 25402228, 2014).
colorectal cancer (7 papers, 2016 to 2025). A primary or metastatic malignant neoplasm that affects the colon or rectum. "Their work showed that ERK2 signaling is responsible for lipid synthesis mediated by cytoplasmic-localized malic enzyme 1 (ME1) phosphorylation, which is overexpressed in a variety of cancers (including colorectal cancer)." (PMID 35646888, 2022). "However, immunohistochemical staining of malic enzyme 1 (ME1) that facilitates glutamine breakdown in 1,260 colorectal carcinoma tissue specimens showed that glutaminolysis was important for locoregional tumor growth but not for metastasis formation." (PMID 27652323, 2016). "We reasoned that increased expression levels of ME1 in human colorectal carcinomas in vivo could be an indicator for the ability of the tumour to maintain optimal energy supply under varying glucose concentrations." (PMID 26948869, 2016). "USP19 antagonizes RNF1-mediated degradation of ME1 through deubiquitination, thereby promoting lipid metabolism and NADPH production while suppressing ROS, consequently triggering the progression of colorectal cancer." (PMID 39944823, 2025).
Hepatic steatosis (7 papers, 2012 to 2025). Steatosis is a term used to denote lipid accumulation within hepatocytes. "The strong positive associations of hepatic ME1 and steatosis, as we reported in a previous study for male, and herein, in female mice, highlight ME1 as a potential drug target to counter fatty liver disease." (PMID 37047583, 2023). "Several studies have shown that ME1 may be involved in adiposity and hepatic steatosis." (PMID 38836220, 2024). "To understand the possible mechanisms involved in the amelioration of hypertriglyceridemia and hepatic steatosis by CBX, we studied the gene expression of lipogenic genes, SCD1 and ME1." (PMID 23284633, 2012). "The expression levels of ACSL5, APOA4 and ME1 in F0 chickens with fatty liver were higher than those in chickens without fatty liver (p < 0.05), but the differences were highly significant in the F1 generation (p < 0.01)." (PMID 29642504, 2018).